APLP2 (amyloid beta precursor like protein 2)
Description:
May play a role in the regulation of hemostasis. The soluble form may have inhibitory properties towards coagulation factors. May interact with cellular G protein signaling pathways. May bind to the DNA 5'-GTCACATG-3'(CDEI box). Inhibits trypsin, chymotrypsin, plasmin, factor XIA and plasma and glandular kallikrein. Modulates the Cu/Zn nitric oxide-catalyzed autodegradation of GPC1 heparan sulfate side chains in fibroblasts (By similarity).
Synonyms: APLP-2; CDEBP; APPL2; APPH
Tractability: Antibody: UniProt places it where antibodies can reach, with high confidence; its Gene Ontology location is reachable by antibodies, with high confidence; UniProt predicts a signal peptide or a membrane-spanning region. PROTAC: ubiquitination databases record sites on it; its protein half-life has been measured.
Gene: Protein-coding gene on chromosome 11 (130,068,147 to 130,144,811, forward strand). Ensembl gene ENSG00000084234.
Subcellular location: Cell membrane; Nucleus
Subcellular location (Human Protein Atlas): Golgi apparatus; Vesicles
Pathways (Reactome):
Metabolism of proteins: Post-translational protein phosphorylation; Regulation of Insulin-like Growth Factor (IGF) transport and uptake by Insulin-like Growth Factor Binding Proteins (IGFBPs)
Hemostasis: Platelet degranulation
Gene Ontology:
Molecular function: identical protein binding; protein binding; serine-type endopeptidase inhibitor activity; DNA binding; heparin binding; transition metal ion binding
Biological process: axonogenesis; central nervous system development; G protein-coupled receptor signaling pathway
Cellular component: extracellular exosome; membrane; nucleus; endoplasmic reticulum lumen; plasma membrane; platelet alpha granule membrane; platelet alpha granule
Genetic constraint (gnomAD): Loss-of-function variants: 48 observed, 84.44 expected, observed/expected ratio (o/e) 0.57, 90% interval 0.45 to 0.72. The upper end of that interval is the gene's LOEUF score, 0.72, which puts it in group 2 of 6, group 1 being the genes least tolerant of losing a copy. Missense variants: 961 observed, 991.44 expected, observed/expected ratio (o/e) 0.97, 90% interval 0.92 to 1.02. Synonymous variants: 365 observed, 354.57 expected, observed/expected ratio (o/e) 1.03, 90% interval 0.94 to 1.12.
Homologues: Orthologues: chimpanzee APLP2 (99% identical), dog APLP2 (95% identical), pig APLP2 (93% identical), rat Aplp2 (93% identical), mouse Aplp2 (93% identical), guinea pig APLP2 (88% identical), rabbit APLP2 (86% identical), macaque APLP2 (85% identical), tropical clawed frog aplp2 (78% identical), zebrafish aplp2 (71% identical), Drosophila melanogaster Appl (29% identical), Caenorhabditis elegans apl-1 (26% identical). Paralogues in human: APP (50% identical), APLP1 (36% identical).
Diseases named in the same sentence as APLP2 in open-access papers:
APLP2 is named in the same sentence as 65 diseases in open-access papers, as found by Europe PMC text mining. Sharing a sentence is not in itself a finding about the gene and the disease. The quoted sentences say what the papers report.
Alzheimer disease (13 papers, 2011 to 2024). A progressive, neurodegenerative disease characterized by loss of function and death of nerve cells in several areas of the brain leading to loss of cognitive function such as memory and language. "The Aplp2 codes for the amyloid-beta precursor protein that produces amyloid-β toxin in humans with Alzheimer’s disease." (PMID 38334607, 2024). "Among these, APLP2 also regulates proper progression of neuronal differentiation program during cortical development, is involved in Alzheimer disease and interacts with CNTN in neurodevelopment and diseases." (PMID 28993790, 2017). "Recent studies have examined possible associations of miR-153 with Alzheimer's disease after functional studies confirmed an interaction with APP and amyloid beta precursor-like protein 2 (APLP2) mRNA transcripts." (PMID 24133413, 2013). "Moreover, APLP2 was the most significantly enriched protein in the cerebrospinal fluid (CSF) of neuronal Vps35 KO mice, and in human Alzheimer’s disease patients." (PMID 37248224, 2023). "APLP2, like APP, has been implicated in Alzheimer’s disease, although APLP2’s sequence does not include the β-amyloid peptide found within APP." (PMID 22797723, 2012). "Alternative splicing of Amyloid precursor-like protein 2 (Aplp2) is known to regulate inclusion of a bovine pancreatic trypsin inhibitor (BPTI) Kunitz domain and this domain is known to regulate proteolysis of the related protein APP, the amyloid precursor protein implicated in Alzheimer’s disease." (PMID 30977723, 2019). "Klotho is an amyloid precursor protein (APP)- and APP-like Protein 2 (APLP2)-dependent gene that is regulated by the large secreted ectodomain fragment soluble (APPsβ), and therefore, it may play a role in the development of Alzheimer’s disease." (PMID 26599613, 2015). "Thus, evidence indicates that miR-153 contributes to post-transcriptional regulation of APP/APLP2 and may therefore have a role in Alzheimer's disease, although further validation of this potential interaction is required." (PMID 24133413, 2013). "APLP1, APLP2, and APP are well-established substrates of β-site amyloid precursor protein cleaving enzyme 1 (BACE1), playing crucial molecular roles in Alzheimer’s disease." (PMID 38370359, 2024). "The amyloid precursor protein (APP), a key player in Alzheimer’s disease (AD), is part of a larger gene family, including the APP like proteins APLP1 and APLP2." (PMID 37533067, 2023). "Aplp1 and Aplp2 are members of the amyloid precursor protein (APP), which is the source of the neurotoxic amyloid beta (Aβ) peptide involved in Alzheimer’s disease (AD)." (PMID 32759773, 2020). "In research to develop improved treatments for Alzheimer’s disease, there has been considerable investigation of the cleavage of APP and APLP2, and inhibitors of β-secretases have been developed that block the cleavage of these proteins." (PMID 22797723, 2012). "While the ablation of Cav1 leads to molecular and cellular changes in mice that are the hallmarks of Alzheimer’s disease, the role of Aplp2 in neurodegeneration in mice is not known." (PMID 38334607, 2024). "Despite its key role in Alzheimer's disease (AD) pathogenesis, the physiological functions of the β-amyloid precursor protein (APP) and its close homologue, the β-amyloid precursor-like protein 2 (APLP2), are still poorly understood." (PMID 21435241, 2011). "Our results suggest that although no chemical inhibitors have been designed with the specific goal of targeting APLP2, existing beta-secretase inhibitors that have been made to target APP for the treatment of Alzheimer's disease may potentially be repurposed to target APLP2." (PMID 26840089, 2016). "Throughout the progression of Alzheimer’s disease, the synaptic transmission-expressed VGLUT2 protein demonstrates downregulation in the absence of both APP and amyloid precursor-like protein 2 (APLP2)." (PMID 38370359, 2024).
pancreatic cancer (13 papers, 2012 to 2025). "To gain a deeper understanding of the role of APLP2 in pancreatic cancer development, we generated a new variant of the KPC mouse model that had APLP2 deficiency in the pancreas." (PMID 33810510, 2021). "In this study, we discovered that the down-regulation of APLP2 in pancreatic cancer cells caused major changes in the actin cytoskeleton in vitro and in the composition of covalently linked actin-positive complexes in pancreatic tumors in vivo." (PMID 25576918, 2015). "Loss of APLP2 decreased cortical actin and increased intracellular actin filaments in pancreatic cancer cells." (PMID 25576918, 2015). "High APLP2 expression in primary pancreatic and metastatic liver lesions was also found to be associated with lower levels of tumor differentiation: 7/8 and 1/8 strongly APLP2-positive sections were from moderately and poorly (respectively) differentiated stages of pancreatic cancer patient tissue." (PMID 25576918, 2015). "In the genetically engineered KRAS-G12D-driven KPC-mouse model for spontaneous pancreatic cancer, deletion of APLP2 significantly prolonged survival and reduced metastasis." (PMID 41362608, 2025). "APLP2 was also reported to be highly expressed in pancreatic cancer cell lines, especially the APLP2 C-terminal fragment and the APLP2-modified glycosaminoglycan in relation to APP full-length and C-terminal fragments." (PMID 39123408, 2024). "Previous research has highlighted the dysregulation of APLP2 in various cancer types, including colorectal, lung, breast, and pancreatic cancers." (PMID 38098487, 2023). "The establishment of these novel mouse strains will provide numerous avenues of investigation for defining the functions of APLP2 in the development and progression of pancreatic cancer." (PMID 33810510, 2021). "We also generated a new mouse model that demonstrated the deletion of APLP2 expression specifically within the pancreas prolongs survival and decreases metastasis for mice with pancreatic cancer." (PMID 33810510, 2021). "Knockdown of APLP2 and APP were observed to reduce pancreatic cancer cell growth by more than 60%, and S2-013 cells treated with a β-secretase inhibitor prevented the formation of APLP2 C-terminal fragments and decreased growth." (PMID 34066808, 2021). "Overall, we have found that APLP2 protein expression increases as pancreatic cancer develops in KPC mice." (PMID 33810510, 2021). "Downregulation of APLP2 in pancreatic cancer changed actin cytoskeletons, diminished migration and invasion, and restricted metastatic spread." (PMID 34066808, 2021). "According to previous research, amyloid precursor-like protein 2 (APLP2) is highly expressed in pancreatic cancer." (PMID 34066808, 2021). "Results from our laboratory demonstrated that the transfection of pancreatic cancer cells in vitro with APLP2 short interfering RNA (siRNA) reduced their growth, and transfection with either APLP2 short hairpin RNA (shRNA) or siRNA reduced their migration." (PMID 33810510, 2021). "Overall, our findings demonstrate the contribution of APLP2 as a potentiating factor in pancreatic cancer development and progression, and thus support future studies to evaluate APLP2 as a preventative or therapeutic target." (PMID 33810510, 2021). "Our work in this study has confirmed APLP2 as a highly expressed regulator of pancreatic cancer, expanding upon past research from our laboratory that indicated APLP2 has an important role in this disease." (PMID 33810510, 2021). "In an effort to further understand APLP2′s influence on pancreatic cancer development, we have turned to autochthonous mouse models of pancreatic cancer." (PMID 33810510, 2021).
pancreatic cancer (continued). "Previous work from our laboratory and other research groups has shown that APLP2 is increased in expression in a variety of human cancers, including Ewing sarcoma, breast cancer, and pancreatic cancer." (PMID 33810510, 2021). "Our previous studies also showed that knockdown of APLP2 by APLP2-specific shRNA significantly inhibited xenograft pancreatic tumor growth and reduced metastasis to the intestine, diaphragm, and kidney in athymic nude mice." (PMID 33810510, 2021). "We also investigated the expression of APLP2 in human pancreatic cancer metastases, and found that APLP2 is increased in metastatic lesions at many sites, particularly the intestine and the diaphragm." (PMID 26840089, 2016). "We incubated pancreatic cancer cells with inhibitors of the beta-secretase enzyme, and observed a reduction in APLP2 C-terminal fragments in the cells." (PMID 26840089, 2016). "In an orthotopic mouse model of pancreatic cancer, we demonstrated that down-regulation of APLP2 expression resulted in decreased tumor weight and limited metastasis." (PMID 26840089, 2016). "Together, our findings indicate that APLP2 influences actin structures and supports specific attributes of pancreatic cancer cells (such as migration and invasion) that contribute to metastasis." (PMID 25576918, 2015). "Consistent with these in vivo findings, in our earlier analysis of APLP2′s effects on pancreatic cancer cell lines, we had also found that once APLP2 expression is down-regulated, pancreatic cancer cells cannot resume their normal growth rate." (PMID 25576918, 2015). "In pancreatic cancer cells, we have observed association of the major histocompatibility complex (MHC) class I molecule with APLP2." (PMID 25576918, 2015). "Accordingly, we found that the high APLP2 expression in a pancreatic cancer cell line clearly increases its mobility and invasion capabilities." (PMID 25576918, 2015). "APLP2 expression was also determined in a separate set of pancreatic cancer tissue array samples, which contained patient-matched primary and metastasis samples." (PMID 25576918, 2015). "Stable knock-down of APLP2 expression (with inducible shRNA) in pancreatic cancer cells reduced the ability of these cells to migrate and invade." (PMID 25576918, 2015). "To investigate the effect of APLP2 on pancreatic cancer cell mobility and invasion, we transfected the pancreatic cancer cell line S2-013 with doxycycline (Dox)-inducible APLP2-shRNA." (PMID 25576918, 2015). "In this study, we investigated the expression of APLP2 in metastatic lesions from the liver, diaphragm, and small intestine of pancreatic cancer patients, as well as in primary pancreatic cancer adenocarcinomas and normal pancreatic tissue." (PMID 25576918, 2015). "Here we showed that APLP2 is increased in pancreatic cancer metastases, particularly in metastatic lesions found in the diaphragm and intestine." (PMID 25576918, 2015). "By our laboratory and others, amyloid precursor-like protein 2 (APLP2) is expressed at a high level in pancreatic cancer cell lines." (PMID 25576918, 2015). "We noted that APLP2 down-regulation in pancreatic cancer cells alters the actin cytoskeleton and decreases migration and invasion." (PMID 25576918, 2015). "Pancreatic tumors in which APLP2 expression was down-regulated by induction of APLP2 shRNA expression were smaller and more restricted in metastatic spread." (PMID 25576918, 2015). "According to our recent studies, APLP2 is also over-expressed in human primary pancreatic tumors, relative to its level in normal human pancreatic ductal epithelial cells." (PMID 25576918, 2015). "Down-regulation of APLP2 decreased the weight and metastasis of orthotopically transplanted pancreatic tumors in nude mice." (PMID 25576918, 2015). "Our pancreatic tumor xenograft experiments also indicated that APLP2 has a profound impact on tumor spread, significantly increasing metastasis to sites in the intestine, kidney, and diaphragm." (PMID 25576918, 2015).
pancreatic cancer (continued). "To address this question, we determined the expression of APLP2 in a series of cell lines generated from the hTERTHPNE cell line, which has been well characterized and used previously in several pancreatic cancer studies." (PMID 22797723, 2012). "In this study, our findings have revealed several new aspects of the relationship between APLP2 and pancreatic cancer." (PMID 22797723, 2012). "In this study, we found comprehensive expression of APLP2 C-terminal fragments in a panel of pancreatic cancer cell lines; however, APP C-terminal fragments were notably limited to the BxPC3 cell line." (PMID 22797723, 2012). "First, APLP2 is highly expressed in human pancreatic cancer cell lines and clinical tissue samples, relative to normal pancreatic tissues." (PMID 22797723, 2012). "Extensive glycosaminoglycan modification on APLP2 was also found in the majority of pancreatic cancer cell lines." (PMID 22797723, 2012). "Since we had observed increasing APLP2 expression with transformation of pancreatic cancer cells, we then determined the contribution of APLP2 to the growth of S2-013 cells." (PMID 22797723, 2012). "In order to test the impact of blocking APLP2 cleavage on the growth of pancreatic cancer cells, we incubated S2-013 cells with chemical inhibitors of the β-secretase enzymes, which subsequently reduced the production of APLP2 C-terminal fragments within 24 h." (PMID 22797723, 2012). "Chiefly, our discoveries establish a role for APLP2 in the growth of pancreatic cancer cells and show that inhibitors preventing APLP2 cleavage reduce the viability of pancreatic cancer cells." (PMID 22797723, 2012). "Downregulation of APLP2 and APP expression, alone or in combination, caused a decrease in the growth of a pancreatic cancer cell line with representatively low APP C-terminal fragment expression, the S2-013 cell line." (PMID 22797723, 2012). "We determined the expression of C-terminal fragments for APP and APLP2 in our panel of pancreatic cancer cell lines by western blot analysis." (PMID 22797723, 2012). "Higher APLP2 expression was found throughout all 8 pancreatic cancer samples: in 5 samples, APLP2 staining was detected at a strong level, and in 3 samples at a moderate level." (PMID 22797723, 2012). "In our current studies, we have identified increased APLP2 in human pancreatic cancer tissues, as compared to normal pancreatic tissues, and have investigated the forms of APLP2 expressed in pancreatic cancer cell lines." (PMID 22797723, 2012). "The pancreatic cancer cell line S2-013 was used as a positive control for APLP2 forms observed in pancreatic cancer cell lines." (PMID 22797723, 2012). "We then reduced expression of APLP2 and APP by co-transfection with both siRNAs to determine if loss of both proteins would further restrict the growth of pancreatic cancer cells." (PMID 22797723, 2012). "Additional work by our research group showed that APLP2 is highly expressed in pancreatic cancer cells, and its presence in these cells increases their migration and growth, facilitates pancreatic tumor metastasis, and shortens the survival of pancreatic tumor-bearing mice." (PMID 40265027, 2025). "APLP2 is able to alter the actin cytoskeleton and promote pancreatic cancer growth and metastasis." (PMID 39123408, 2024). "To study the role of APLP2 in pancreatic cancer initiation and progression, we generated a variant of the KPC model with a conditional, pancreas-specific knockout of APLP2, thus allowing for longitudinal investigation of the impact of APLP2 on pancreatic cancer development." (PMID 33810510, 2021). "In this current study, we showed that the expression of amyloid precursor-like protein 2 (APLP2) in pancreatic cancer epithelial cells is higher than in precursor lesion epithelial cells, thus indicating that APLP2 increases during human pancreatic cancer development." (PMID 33810510, 2021).